ARSD (arylsulfatase D)
Synonyms: ASD
Tractability: Antibody: UniProt predicts a signal peptide or a membrane-spanning region. PROTAC: its protein half-life has been measured.
Gene: Protein-coding gene on chromosome X (2,903,972 to 2,929,405, reverse strand). Ensembl gene ENSG00000006756.
Subcellular location: Lysosome
Subcellular location (Human Protein Atlas): Lipid droplets; Vesicles
Pathways (Reactome):
Metabolism: Glycosphingolipid catabolism
Metabolism of proteins: The activation of arylsulfatases
Gene Ontology:
Molecular function: arylsulfatase activity
Cellular component: endoplasmic reticulum lumen; lysosome
Homologues: Orthologues: chimpanzee ARSD (99% identical), macaque ARSD (96% identical), dog ARSD (80% identical), pig ARSD (76% identical), guinea pig ARSD (56% identical), tropical clawed frog arsh (55% identical), zebrafish arsh (34% identical), Caenorhabditis elegans sul-2 (24% identical), Drosophila melanogaster CG7402 (23% identical), Drosophila melanogaster CG7408 (23% identical), Drosophila melanogaster CG32191 (23% identical), Drosophila melanogaster Sulf1 (18% identical), and 3 more. Paralogues in human: ARSL (62% identical), ARSH (60% identical), ARSF (58% identical), STS (48% identical), ARSG (30% identical), GALNS (30% identical), ARSA (28% identical), ARSI (24% identical), ARSJ (22% identical), ARSB (22% identical), SULF2 (20% identical), IDS (20% identical), and 4 more.
Diseases named in the same sentence as ARSD in open-access papers:
ARSD is named in the same sentence as 12 diseases in open-access papers, as found by Europe PMC text mining. Sharing a sentence is not in itself a finding about the gene and the disease. The quoted sentences say what the papers report.
breast carcinoma (3 papers, 2021 to 2023). "As the downstream signal of ERα, ARSD is able to restrain YAP/TAZ activation and cancer cell proliferation through acting on the Hippo signaling pathway, implying that ARSD can be a potential target in breast cancer." (PMID 37576865, 2023). "Herein, we provided solid evidences that ARSD, as a novel ERα downstream target gene, inhibits proliferation and migration of breast cancer cells via activating Hippo/YAP pathway." (PMID 34725332, 2021). "According to Lin’s findings, increased expression of ARSD might contribute to amyloidosis in breast cancer cells, and therefore targeting ARSD could be a potential strategy for treating TNBC or Alzheimer’s disease (AD)." (PMID 37766864, 2023). "Additionally, ARSD might function as a molecular inhibitor of the ERα signaling pathway by preventing uncontrolled activation of ERα in breast cancer cells." (PMID 37766864, 2023).
glioma (2 papers, 2023 to 2024). A benign or malignant brain and spinal cord tumor that arises from glial cells (astrocytes, oligodendrocytes, ependymal cells). "Survival analysis indicated that individuals with high ARSD expression in glioma had a shorter survival time." (PMID 37766864, 2023). "We performed a pan-cancer analysis of ARSD, and investigated the relationship between expression of ARSD and overall survival (OS) in multiple glioma datasets." (PMID 37766864, 2023). "Using CCK-8 and Transwel, we found the increased proliferation, migration, and invasion of glioma cells induced by ARSD overexpression were reversed upon inhibition of the JAK2/STAT3 signaling pathway with AG490." (PMID 37766864, 2023). "High level of ARSD promoted the development of glioma by regulating M2 macrophage infiltration and JAK2/STAT3 pathway." (PMID 37766864, 2023). "In vitro experiment showed that ARSD can promote glioma cell proliferation through JAK2/STAT3 pathway and regulate M2 macrophage infiltration." (PMID 37766864, 2023). "Combined with cell experiment and bioinformatic analysis, we found that ARSD can promote glioma progression through regulation of JAK2/STAT3 pathway and M2 macrophage infiltration." (PMID 37766864, 2023). "Glioma tissue samples were collected to verify the expression of ARSD in glioma, while the functions of ARSD were explored using cell experiment." (PMID 37766864, 2023). "We then performed cell experiment to investigate the roles of ARSD in glioma." (PMID 37766864, 2023). "Based on these results, targeting ARSD may represent a promising approach for preventing the infiltration of macrophages by glioma cells." (PMID 37766864, 2023). "Our work revealed the roles of ARSD in anti-tumor immunity of glioma, and found that ARSD expression exhibited a positive correlation with the scores of Step4 and Step1 in the Cancer-Immunity Cycle, while displaying a negative correlation with the scores of Step7, Step5, Step3, and Step2." (PMID 37766864, 2023). "Further investigation has shown the mechanisms of ARSD for glioma using bioinformatic analysis." (PMID 37766864, 2023). "In this study, we discovered that ARSD was upregulated in glioma and could serve as a novel prognostic predictor." (PMID 37766864, 2023). "Besides, our results further revealed that the upregulation of ARSD, which promoted glioma cell proliferation, migration and invasion, could be effectively inhibited by the JAK2/STAT3 pathway inhibitor AG490." (PMID 37766864, 2023). "Although several researches have revealed the functions of ARSD in tumor progression, the prognostic value of ARSD in glioma and the related mechanisms have not been fully investigated." (PMID 37766864, 2023). "However, the roles of ARSD and its molecular mechanism have not been investigated in glioma." (PMID 37766864, 2023).
breast tumor (1 paper, 2021). "Meanwhile, a reduced ARSD expression level was observed in breast tumor tissues or metastatic breast tissues when compared with normal breast tissues (p = 1.37e-08)." (PMID 34725332, 2021).
chronic lymphocytic leukemia (1 paper, 2014). "The ARSD gene encodes a sulfatase that is associated with bone and cartilage development and has been identified previously as having involvement in sphingolipid metabolism (involved in signal transmission and cellular recognition) and as a potential biomarker for chronic lymphocytic leukemia." (PMID 25372662, 2014).
esophageal adenocarcinoma (1 paper, 2023). A malignant tumor with glandular differentiation arising predominantly from Barrett mucosa in the lower third of the esophagus. "ARSD alterations occur in a variety of tumors, such as deep in esophageal adenocarcinoma deletion, mutation in UCEC and GBM." (PMID 37766864, 2023).
invasive ductal breast carcinoma (1 paper, 2021). The most common type of invasive breast carcinoma, accounting for approximately 70% of breast carcinomas. "Interestingly, in 11 analyses with ARSD under-expression, ARSD expression mainly reduced in invasive ductal breast carcinoma compared with other types of BC." (PMID 34725332, 2021).
tumor (6 papers, 2009 to 2024). "The immunohistochemical analysis revealed the increase of ARSD expression with higher tumor grades." (PMID 37766864, 2023). "Overall, ARSD exhibits higher expression level in normal breast tissue compared with cancer tissue, which may play a tumor suppression role in BC." (PMID 34725332, 2021). "Moreover, ssGSEA showed that ARSD expression was correlated with the extracellular matrix organization pathway (Top one enrichment), indicating that ARSD may serve as a regulatory factor in tumorigenesis and tumor progression." (PMID 38895621, 2024). "We thereafter speculated that ARSD may be as a novel tumor suppressor in BC." (PMID 34725332, 2021). "Of these, 8 genes showed a significant decrease in expression in tumor samples with this deletion relative to tumors samples without this deletion: ARSD, ARSE, MXRA5, PRKX, LOC729137, NLGN4X, HDHD1A, and STS." (PMID 19419571, 2009).
cancer (5 papers, 2017 to 2024). A tumor composed of atypical neoplastic, often pleomorphic cells that invade other tissues. "Specifically, NEFH, hepatitis A virus cellular receptor 1 (HAVCR1, 5q33.2), interferon, alpha-inducible protein 27 (IFI27, 14q32), PCSK5, and the arylsulfatase D gene (ARSD, Xp22.3) have been implicated in a variety of cancers." (PMID 28249600, 2017). "Pan-cancer analysis demonstrated that ARSD was aberrantly expressed in most cancer types of TCGA." (PMID 37766864, 2023). "Moreover, our results revealed that ARSD was involved in various steps of the Cancer-Immunity Cycle." (PMID 37766864, 2023). "Taken together, these data suggest that the ARSD expression in breast tissue may protect from women to cancer." (PMID 34725332, 2021).
ARSD also shares sentences with these, for which no sentence is quoted: amyloidosis (2 papers); Alzheimer disease (1); diabetes (1); genetic diseases (1).